CAV1 (caveolin 1)
Diseases named in the same sentence as CAV1 in open-access papers (continued):
Sharing a sentence is not in itself a finding about the gene and the disease.
breast carcinoma (continued). "Caveolin-1 has been reported to be downregulated in a number of human breast cancer cell lines as well as in tumours derived from transgenic rodents with breast cancer." (PMID 17915016, 2007). "Included in the list of 102 genes are genes previously identified as being hypermethylated and down-regulated in cancer (e.g., zinc finger protein 185 in prostate cancer, CAV1 in breast cancer, and DIRAS3 in ovarian cancer)." (PMID 17254359, 2007). "In mammary tumours induced in mice by targeted overexpression of ErbB2, caveolin-1 was also down-regulated, as it was in tumours induced by overexpression of the downstream molecules Ras and Src." (PMID 18949068, 2007). "We have previously linked the tumorigenic phenotype of Comma/PDK1 cells to the disappearance of another breast cancer tumor suppressor, caveolin-1." (PMID 16551362, 2006). "In summery, our results indicated that CAV1 suppression correlated closely with that of CAV2 in breast cancer, that CAV1 level was inversely correlated with tumour size, and that CAV1 and CAV2 levels were correlated with hormonal receptor status." (PMID 15305200, 2004). "Our results indicated that CAV1 suppression correlated closely with that of CAV2 in breast cancer, that CAV1 level was inversely correlated with tumour size, and that CAV1 and CAV2 levels were correlated with hormonal receptor status." (PMID 15305200, 2004). "CAV1 has been reported to interact with various intracellular signalling pathways and is thought to suppress tumour growth in breast cancer cell lines." (PMID 15305200, 2004). "The expression of caveolin-1 is elevated in various cancer tissues, including prostate cancer, oesophageal squamous cell carcinoma, colon cancer and breast cancer." (PMID 12402154, 2002). "However, P4 increased the formation of PR-Csk and PR-caveolin-1 in the SHP2 knockdown breast cancer cell lines." (PMID 39996064, 2025). "The nanodrugs could be internalized into breast cancer cells through both clathrin and CAV‐1‐mediated endocytosis and generate ROS in an NQO1‐dependent manner." (PMID 40150864, 2025). "Moreover, P4 increased the activities of cSrc negative regulatory proteins (p-Csk and p-caveolin-1) in these SHP2 knockdown breast cancer cell lines." (PMID 39996064, 2025). "However, the expression of CAV1 is downregulated in breast cancer and ovarian cancer, suggesting that CAV1 has a biphasic function." (PMID 40419438, 2025). "By modulating Cav‐1's CSD, it is possible to inhibit TGF‐β‐induced Smad phosphorylation, which could potentially reduce breast cancer risk in SSc patients." (PMID 40778471, 2025). "Furthermore, in MCF-7 breast cancer cells, the co-expression of Cav-1 and Kv1.5 significantly enhances cell survival." (PMID 40358155, 2025). "Among breast related diseases, reports on Cav-1 and autophagy mainly focus on breast cancer." (PMID 41030451, 2025). "Separately, a mechanistic study using the Cancer Genome Atlas (TCGA) data and breast cancer models demonstrated that PDGFRβ, along with caveolin-1 (Cav-1), promotes autophagy in CAFs through the mTOR/FIP200/ATG13 pathway and enhances tumor invasiveness via HIF-1α/MCT4/MCT1 signaling." (PMID 41441395, 2025). "Knockdown of SHP2 increased the complex formations of cSrc-Csk, cSrc-p140Cap and cSrc-p-caveolin-1, subsequently inducing phosphorylation of cSrc at tyrosine 527 and inactivation of cSrc, and eventually abolished the P4-promoted breast cancer proliferation and migration." (PMID 39996064, 2025). "However, the low expression of some markers, such as caveolin 1 scaffold protein, in CAFs is related to a more advanced tumor stage, early cancer recurrence, lymph node metastasis, and poor disease prognosis in breast cancer." (PMID 40940764, 2025).
breast carcinoma (continued). "have revealed that the anticancer drug Sanguisorba officinalis L (SA) plays an anti-tumor metastasis role in breast cancer by inhibiting hypoxia inducible factor-1α (Hif-1 α)/Cav-1 signaling, thereby affecting lysosomal function and inhibiting late stage of autophagy." (PMID 41030451, 2025). "Additionally, Cav-1 and Wnt7a in EXOs released by breast cancer cells enhance tumor angiogenesis through different signaling pathways." (PMID 40486870, 2025). "Previous studies have shown that basal-type and post-EMT breast cancer cell lines are particularly sensitive to dasatinib, with elevated expression of genes such as moesin (MSN), caveolin-1 (CAV1), and yes-associated protein-1 (YAP1), which are associated with the SRC signaling pathway." (PMID 41462902, 2025). "Additionally, breast cancer-derived exosomes containing Caveolin-1 (Cav-1) modulate inflammatory gene expression in lung epithelial cells, regulating matrix deposition in lung fibroblasts." (PMID 40028322, 2025). "Moreover, siRNA-mediated silencing of Cav-1 results in the activation of BKCa channels and enhances their surface expression, thereby driving breast cancer cell proliferation and invasiveness." (PMID 40358155, 2025). "It was recently revealed that breast cancer cells-derived exosomal caveolin-1 (Cav-1) could promote ECM deposition in lung fibroblasts as well as inhibit the PTEN/CCL2/VEGF-A signaling pathway in lung macrophages, thus contributing to the PMN formation." (PMID 38802766, 2024). "Furthermore, it enhances the activity of the Cav-1/NF-κB/c-Myc pathway in both the transgenic MMTV-PyVT breast cancer spontaneous model and the zebrafish breast cancer xenotransplantation model, without any reported adverse effects." (PMID 38563878, 2024). "Differences in experimental approaches, cell lines, and specific contexts may contribute to the contradictory results regarding the role of Cav-1 in breast cancer metastasis." (PMID 39244591, 2024). "Therefore, it was not possible to definitively infer which cell types CAV1 was located in47 and, subsequently, the role CAV1 plays in these cell types in the context of breast cancer." (PMID 38509243, 2024). "They accomplished this by utilizing both a CAV-1 overexpression plasmid and siRNA and demonstrated that AS-IV suppresses the expression of CAV-1 and stimulates the endothelial nitric oxide synthase/nitric oxide pathway, thereby enhancing the chemical responsiveness of breast cancer to paclitaxel." (PMID 39064966, 2024). "Notably, CAV1 protein expression in stromal cells has been reported as a potential prognostic biomarker in breast cancer." (PMID 38959243, 2024). "Studies indicated that the increase in MCT4 is associated with a poor prognosis in breast cancer patients, and the absence of stromal Cav1 indicated early tumor recurrence and poor clinical outcomes." (PMID 38361760, 2024). "Cav-1 in exocrine bodies derived from Breast cancer (BC) can be used as signal molecules to promote the secretion of tenascin-C in lung fibroblasts and lead to the deposition of ECM, which mediates intercellular communication and regulates premetastatic niche (PMN) before lung metastasis." (PMID 37978384, 2023). "In addition, Cav-1 can also act on integrin, another important molecule, to promote the invasion and migration of breast cancer cells." (PMID 37828916, 2023). "Therefore, Cav-2, Cav-3 and Cav-1 can also act as related regulatory factors in breast cancer progression and play dual roles in cancer inhibition and promotion." (PMID 37828916, 2023). "The expression of Cav-1 in breast cancer with lymph node metastasis is significantly higher than that in breast ductal carcinoma in situ without lymph node metastasis, indicating that the high expression of Cav-1 is related to the invasion and metastasis of breast cancer." (PMID 37828916, 2023).
breast carcinoma (continued). "Epithelial and stromal Cav1 expression were also found to be inversely correlated suggesting that the role of Cav1 may be biphasic in the progression of breast cancer." (PMID 37822942, 2023). "Therefore, it would be of value to further explore adipose tissue regulators, such as CAV1 in breast cancer, considering the complex relationship between obesity and breast cancer." (PMID 37017811, 2023). "However, the specific role of Cavin-1 and Cav-1 in regulating IGF-IR in breast cancer is still controversial and needs further study." (PMID 37828916, 2023). "In addition, high expression of Cav-1 in breast cancer is indicative of breast cancer sensitivity to albumin-paclitaxel." (PMID 37828916, 2023). "In vitro cell experiments showed that Scleromitrion diffusum can effectively inhibit the metastasis of breast cancer cells, possibly by inhibiting the expression of Cav-1 protein, thereby reducing matrix metalloproteinases (MMPs) and inhibiting its ability to invade and migrate." (PMID 37828916, 2023). "Taken together, this indicates that the obese normal-weight phenotype, which might be captured by the CAV1 genotype, favors the development of metachronous contralateral breast cancer and locoregional recurrence whereas obesity favors distant recurrences." (PMID 37017811, 2023). "In addition, the expression of Cav-1 in stromal cells was negatively correlated with the expression of estrogen receptor (ER) in breast cancer and positively correlated with tumor metastasis traits." (PMID 37828916, 2023). "At present, there are two views on the correlation between Cav-1 and breast cancer: 1) Cav-1 acts as a suppressor gene of breast cancer, which inhibits the malignant process of breast cancer; 2) Cav-1 expression promotes the occurrence and development of breast cancer." (PMID 37828916, 2023). "Cav-1 inhibits the production of autophagic lysosomes by blocking the fusion of lysosomes and autophagosomes, thus blocking autophagic flow and inhibiting the proliferation of breast cancer cells." (PMID 37828916, 2023). "Similarly, our work supports the idea that Cav1 levels are lower in the stroma of black women with breast cancer." (PMID 37822942, 2023). "The inactivation of the Cav-1 gene leads to increased (Estrogen Receptor alpha) ERα expression, which can be seen in both human breast cancer epithelial cells and mouse primary breast cancer epithelial cells, and can promote the growth of stimulated three-dimensional epithelioid structures." (PMID 37828916, 2023). "The Cav proteins include Cav-1, Cav-2 and Cav-3, among which Cav-1 has attracted the most attention as a tumor suppressor and promoting factor affecting the proliferation, apoptosis, migration, invasion and metastasis of breast cancer cells." (PMID 37828916, 2023). "This evidence suggests that Cav-1 may promote the invasion and migration of breast cancer by promoting the EMT process." (PMID 37828916, 2023). "In addition, Cav-1 inhibits the self-renewal capacity and aerobic glycolysis of breast cancer stem cells through C-myc-mediated tumor metabolic reprogramming." (PMID 37828916, 2023). "We propose that this could be important in the context of cancer disparities as we also observed increased levels of circulating miR-510-5p and reduced levels of stromal Cav1 in black women compared to white women with breast cancer." (PMID 37822942, 2023). "In addition, Cav-1 can also affect the proliferation of breast cancer by inhibiting aerobic glycolysis in breast cancer (Warburg effect)." (PMID 37828916, 2023). "We propose that miR-510-5p mediated negative regulation of Cav1 in fibroblasts is a novel mechanism of aggressive tumor growth and may be a driver of breast cancer disparity." (PMID 37822942, 2023). "Additionally, CAF expression was higher in metastatic axillary LNs than that in normal/reactive axillary LNs, implying that Cav-1 plays a role in breast cancer metastasis." (PMID 38273859, 2023).
breast carcinoma (continued). "Finally, the role of the HOTAIR/miR-203/CAV1 axis in the proliferation, invasion, and migration of the breast cancer cell line MDA-MB-231 was clarified." (PMID 36233075, 2022). "Furthermore, caveolin-1 (Cav-1) was downregulated in fibroblasts cocultured with breast cancer cells." (PMID 35530337, 2022). "CAV1 levels were evaluated with immunohistochemistry in cytoplasm of invasive tumor cells and stromal cells in tumor tissue microarrays from a cohort of 1018 breast cancer patients (inclusion 2002–2012, Sweden)." (PMID 35660849, 2022). "Previous evidence has shown a regulation of the internal and perimembrane pH via the inhibition of NaV1.5 activity with TTX, and shortly thereafter a colocalization of NaV1.5 sodium channels and NHE-1 exchanger in regions rich in Caveolin-1 at the plasma membrane of breast cancer cells was found." (PMID 36612049, 2022). "Furthermore, the NS1643-dependent dephosphorylation of pY14-Cav1 also occurred when Cav1 was heterologously overexpressed in MCF7 breast cancer cells." (PMID 35954304, 2022). "Metastatic breast cancer cells express high levels of CAV1 as well as elevated levels of Y14 phosphorylation, which are associated with increased cell migration by promoting focal adhesion turnover, polarization, persistency, speed, and directionality of migration." (PMID 35740528, 2022). "CAV1 was identified to be highly expressed in HER2-positive breast-cancer tissues." (PMID 35158857, 2022). "Recently, many researchers suggested that CAFs can regulate different physiological functions of tumor cells, and according to the analyzed data of GEPIA, the CAV-1 expression level is significantly downregulated in breast cancer tissues compared with that in normal tissues." (PMID 36604141, 2022). "Since breast cancer is a heterogeneous disease with different tumor biology, receptor expression, and outcomes, CAV1’s prognostic impact may be context-dependent." (PMID 35660849, 2022). "The expression of CAV1 is epigenetically silenced by methylation in colon- and breast-cancer cells." (PMID 35158857, 2022). "Thus, we investigated the role of CAV1 in signaling pathways and different cellular compartments of breast cancer in relation to clinical outcomes overall and different patient subgroups." (PMID 35660849, 2022). "Thus, PTP1B and Cav-1 expression appear to have apposing roles in mediating breast cancer metastasis." (PMID 35954304, 2022). "As shown inFigure 1C, CAV-1 expression in breast cancer tissues with lymph node metastasis was lower than that in breast tissues without lymph node metastasis, and the EMT and stemness of BCCs with lymph node metastasis were more active than those of BCCs without lymph node metastasis." (PMID 36604141, 2022). "•Cytoplasmic CAV1 was a marker for metachronous contralateral breast cancer." (PMID 35660849, 2022). "For example, mechanical stimulation induces phosphorylation of Cav1 in breast cancer cells." (PMID 35372369, 2022). "Therefore, our team has been devoted to the related research of CAV1, trying to elucidate the mechanism of CAV1 in breast cancer progression." (PMID 36233075, 2022). "To explore whether decreased CAV-1 expression in breast cancer tissue is related to lymph node metastasis, we collected 20 invasive breast cancer tissue specimens from the First Affiliated Hospital of Nanchang University from February 2019 to February 2020." (PMID 36604141, 2022). "In addition, in breast-cancer cells, Rack1 and Src tyrosine kinase regulate P-gp activity by modulating CAV1 phosphorylation." (PMID 35158857, 2022). "Tamoxifen regulates CAV1 in MCF7 breast-cancer cells in a bimodal fashion." (PMID 35158857, 2022). "The dual role of CAV1 in breast cancer deserves further exploration." (PMID 36233075, 2022). "However, we did detect elevated cancer cell growth in Cav-1 depleted breast cancer cells, similar to a previous report." (PMID 35954304, 2022).
breast carcinoma (continued). "Loss of CAV1 in stroma indicated transformation of surrounding tissue into TME through tumor cell and stroma interactions mediated by various signaling pathways, including TGFβ in early breast cancer." (PMID 35660849, 2022). "Here, we explore whether CAV-1-deficient fibroblasts play an essential role in the EMT and stemness of breast cancer cells (BCCs) through TGF-β signaling." (PMID 36604141, 2022). "More importantly, CHIP-PCR assay validated that ursolic acid could promote the binding of SP1 with CAV1 promoter region of breast cancer cells, while SP1 knockdown could partially abrogate that." (PMID 34568078, 2021). "Further investigations demonstrated that ursolic acid may impair the glycolytic metabolism of breast cancer cells by activating Caveolin-1 (Cav-1) signaling, as Cav-1 knockdown could partially abrogate the suppressive effect of ursolic acid on that." (PMID 34568078, 2021). "It has been reported that Cav-1 inhibits breast cancer stem cells through metabolic reprogramming." (PMID 34955837, 2021). "Ursolic acid could significantly elevate Cav-1 expression and induce mitochondrial depolarization in breast cancer cells." (PMID 34568078, 2021). "Interestingly, Cav-1 is thought to be a tumor suppressor, and tumor growth and metastasis were facilitated by Cav-1 downregulation in adipocyte surrounded breast cancer cells." (PMID 33413697, 2021). "Moreover, we show that autophagy resulting from CEMM disruption is involved in doxorubicin (Doxo) resistance in breast cancer cells with low CAV1 expression, while suppression of autophagy by hydroxychloroquine (HCQ) overcomes the drug resistance." (PMID 34786475, 2021). "Notably, among the 10 compounds, ursolic acid also exhibited the strongest induction effect on Cav-1 expression in breast cancer cells." (PMID 34568078, 2021). "It was found that ursolic acid treatment could significantly increase CAV1 mRNA levels in breast cancer cells in a concentration-dependent manner, suggesting that ursolic acid could induce Cav-1 expression by elevating its transcription activity." (PMID 34568078, 2021). "Notably, a loss of stromal Cav-1 expression is a strong predictor of poor clinical outcome in TNBC and basal-like breast cancers." (PMID 33498875, 2021). "Our findings thus provide novel insights into the molecular mechanisms controlling autophagosome biogenesis via SNARE protein in recycling endosomes under the regulation of CEMMs, and the potential clinical target for breast cancer patients with reduced CAV1 expression who develop Doxo resistance." (PMID 34786475, 2021). "The aim of this study was to investigate the expression of Cav-1 in: i) the stromal compartment of axillary lymph nodes of breast cancer patients, to seek a correlation with cancer metastasis; ii) in the stroma of invasive breast carcinomas (IBCs), to confirm data from published studies." (PMID 33531603, 2021). "Therefore, this study was designed to determine the potential compound targeting Cav-1 expression in Oldenlandia diffusa and to explore its pharmacological mechanisms against breast cancer." (PMID 34568078, 2021). "Interestingly, recent report also suggests its involvement of caveolin-1 in DNA damage and repair in breast cancer cells." (PMID 34762666, 2021). "Thus, the combined analysis of MCT4 and CAV-1 expression levels in the matrix can improve the accuracy of breast cancer prognosis." (PMID 33816265, 2021). "Furthermore, it has been found that a decrease in CAV-1 levels in stromal cells in the tumor microenvironment enhances breast cancer resistance to tamoxifen." (PMID 33816265, 2021). "As previous studies have proved that downregulation of CAVIN2 could cause reduction in CAVIN1 and CAV1 expression, the interdependency of these 3 molecules makes CAVIN2 as a prominent therapeutic target in breast cancer treatment." (PMID 34513683, 2021).